COQ5 (coenzyme Q5, methyltransferase)
Description:
Methyltransferase required for the conversion of 2-decaprenyl-6-methoxy-1,4-benzoquinol (DDMQH2) to 2-decaprenyl-3-methyl-6-methoxy-1,4-benzoquinol (DMQH2).
Synonyms: MGC4767; COQ10D9
Tractability: Antibody: UniProt places it where antibodies can reach, with high confidence. PROTAC: ubiquitination databases record sites on it; its protein half-life has been measured.
Gene: Protein-coding gene on chromosome 12 (120,503,279 to 120,534,434, reverse strand). Ensembl gene ENSG00000110871.
Subcellular location: Mitochondrion inner membrane
Subcellular location (Human Protein Atlas): Mitochondria; Nucleoli
Pathways (Reactome):
Metabolism: Ubiquinol biosynthesis
Gene Ontology:
Molecular function: 2-methoxy-6-polyprenyl-1,4-benzoquinol methyltransferase activity; protein binding; methyltransferase activity
Biological process: methylation; ubiquinone biosynthetic process
Cellular component: mitochondrial inner membrane; mitochondrial matrix; mitochondrion; protein-containing complex; ubiquinone biosynthesis complex; extrinsic component of mitochondrial inner membrane
Genetic constraint (gnomAD): Loss-of-function variants: 20 observed, 35.84 expected, observed/expected ratio (o/e) 0.56, 90% interval 0.39 to 0.81. The upper end of that interval is the gene's LOEUF score, 0.81, which puts it in group 3 of 6, group 1 being the genes least tolerant of losing a copy. Missense variants: 360 observed, 382.12 expected, observed/expected ratio (o/e) 0.94, 90% interval 0.86 to 1.03. Synonymous variants: 119 observed, 140.63 expected, observed/expected ratio (o/e) 0.85, 90% interval 0.73 to 0.99.
Gene-disease validity (ClinGen):
ClinGen rates the evidence that COQ5 causes each of these diseases.
mitochondrial disease (autosomal recessive): Moderate.
Homologues: Orthologues: chimpanzee COQ5 (99% identical), macaque COQ5 (97% identical), dog COQ5 (89% identical), rabbit COQ5 (88% identical), pig COQ5 (88% identical), guinea pig COQ5 (87% identical), rat Coq5 (86% identical), mouse Coq5 (84% identical), tropical clawed frog coq5 (68% identical), zebrafish coq5 (65% identical), Drosophila melanogaster Coq5 (49% identical), Caenorhabditis elegans coq-5 (40% identical). Paralogues in human: AS3MT (16% identical), METTL27 (11% identical), TMT1B (10% identical), TMT1A (10% identical).
Diseases named in the same sentence as COQ5 in open-access papers:
COQ5 is named in the same sentence as 20 diseases in open-access papers, as found by Europe PMC text mining. Sharing a sentence is not in itself a finding about the gene and the disease. The quoted sentences say what the papers report.
cerebellar ataxia (4 papers, 2022 to 2024). A neurological syndrome characterized by clumsy and uncoordinated movement of the limbs, trunk, and cranial muscles. "This suggests a specific constellation of clinical traits linked to mutations at the COQ5 locus, so far, encompassing cerebellar ataxia, encephalopathy, developmental delay, short stature, dysarthria, ID, cerebellar atrophy, and COQ10 deficiency in leucocyte assay (respectively)." (PMID 37599337, 2023). "In 2017, three female siblings from a Middle Eastern Iraqi-Jewish descent family presented with early-onset cerebellar ataxia and encephalopathy characterized by cognitive disability and myoclonic-epilepsy, resulting from a biallelic duplication of 9590bp in COQ5." (PMID 38673663, 2024). "It is important to note that a previous report showed a homozygous partial tandem duplication of the 3’ end of the COQ5 gene in 3 affected siblings with varying degree of cerebellar ataxia, encephalopathy, generalized tonic-clonic seizures, and cognitive disability." (PMID 36266294, 2022).
astrocytomas (1 paper, 2022). "Taken together, we have demonstrated that lower CoQ10 levels and protein levels of COQ3, COQ5, COQ6, COQ7, COQ8A, and COQ9 were associated with higher tumor grades and lower CS activity or COX II level in human astrocytomas." (PMID 35204836, 2022). "The levels of COQ3, COQ5, COQ6, COQ7, COQ8A, and COQ9, but not of COQ4, were lower in Grade IV astrocytoma tissues than in controls or low-grade (Grades I and II) astrocytomas, but PDSS2 levels were higher in astrocytoma tissues than in controls." (PMID 35204836, 2022).
Mitochondrial myopathy (1 paper, 2015). "In contrast, in the new Coq9Q95X mouse model reported here, the lack of COQ9 protein results in decreased levels of only COQ7 and COQ5 proteins, which leads to moderate CoQ deficiency and a mild mitochondrial myopathy, especially evident in females." (PMID 25802402, 2015).
myoclonic epilepsy (1 paper, 2022). A group of epilepsy syndromes in which myoclonic seizures are a prominent feature. "It was thereby proven that the decreased ΔΨm and mt ATP levels caused by uncoupler FCCP treatment or MERRF (myoclonic epilepsy with ragged red fibers) mutation could suppress the COQ5 protein maturation." (PMID 36291741, 2022).
neurodevelopmental disorder (1 paper, 2023). A behavioral and cognitive disorder with onset during the developmental period that involves impaired or aberrant development of intellectual, motor, or social functions. "Although each trait may occur individually in many unrelated neurodevelopmental disorders, and also in patient pathology profiles with other COQ loci biallelic mutation, we propose that a majority (5/8 or more) of these traits occurring together represents a core phenotype linked to COQ5 disruption." (PMID 37599337, 2023).
COQ5 also shares sentences with these, for which no sentence is quoted: developmental delay (2 papers); Encephalopathy (2); allergic rhinitis (1); Ataxia (1); atransferrinemia (1); Cerebellar atrophy (1); encephalomyopathy (1); hemochromatosis (1); homocystinuria (1); infection (1); lactic acidosis (1); Leigh syndrome (1); renal failure (1); tonic-clonic seizures (1); tumor (1).